TSHR (thyroid stimulating hormone receptor)
Diseases named in the same sentence as TSHR in open-access papers (continued):
Sharing a sentence is not in itself a finding about the gene and the disease.
ovarian carcinoma (continued). "In the current study, we were surprised to find that, like the gonadotropin receptors, TSHR also exists in normal mammalian OSE and in human ovarian cancers." (PMID 27273257, 2016). "The expression and functional role of TSHR in a variety of non-thyroid cancerous tissues, including melanoma, glioma, lung cancer, breast cancer, ovarian cancer and liver cancer, have been reported." (PMID 32698392, 2020). "Recently, they also discovered that the paracrine thyrostimulin-mediated activation of TSHR switched on canonical G-protein coupled signaling pathways and trans-regulated activation of epithelial growth factor receptor (EGFR) to promote ovarian cancer cell proliferation." (PMID 32698392, 2020). "Therefore, although TSHR signaling has not yet been well characterized in the ovarian cancer cells, one may speculate that it can also activate the calcium and PKC pathways, which may then contribute to at least part of the thyrostimulin-induced ERK activation." (PMID 27273257, 2016).
Primary hypothyroidism (6 papers, 2017 to 2025). A type of hypothyroidism that results from a defect in the thyroid gland. "In conclusion, our data indicate that GRP170 deficiency in thyrocytes leads to a diminished presence of TSHR at the cell surface, thereby accounting for primary hypothyroidism associated with thyroidal TSH resistance." (PMID 40923318, 2025). "We note that a large number of TSHR loss-of-function mutants have been reported to trigger primary hypothyroidism with TSH resistance in humans, including many missense mutants." (PMID 40923318, 2025).
anaplastic thyroid carcinoma (5 papers, 2000 to 2025). "Our previous study showed that the expression of TSHR was enhanced by nevirapine in anaplastic thyroid carcinoma cells." (PMID 32300552, 2020). "We previously showed that nevirapine upregulated TSHR mRNA in anaplastic thyroid carcinoma cells, which could increase the expression of cAMP." (PMID 32300552, 2020). "In our previous study, nevirapine upregulated the levels of NIS and TSHR mRNA, however, to our disappointment, it did not improved the radioiodide uptake significantly in anaplastic thyroid cancer cells." (PMID 32300552, 2020).
athyreosis (5 papers, 2013 to 2025). Athyreosis is a form of thyroid dysgenesis characterized by complete absence of thyroid tissue that results in primary congenital hypothyroidism, a permanent thyroid deficiency that is present from birth. "TD represents approximately 80–85% of CH cases and includes conditions such as ectopy, athyreosis, and orthopic hypoplasia, which are rarely linked to mutations in transcription factor genes like TSHR, PAX8, and NKX2-1." (PMID 40981308, 2025). "However, in that study, when cases with TSHR variants, a gene associated with hypoplasia or apparent athyreosis but neither with ectopy nor with true athyreosis, were excluded, the discovery rate drops to 16%." (PMID 35272499, 2022).
diabetes (5 papers, 2021 to 2025). "Our study demonstrated for the first time through mouse and in vitro experiments that Schwann cells express TSHR and that TSH may enhance oxidative stress and apoptosis in Schwann cells by binding to TSHR, thereby revealing the mechanism by which diabetes combined with SCH exacerbates DPN." (PMID 34804362, 2021). "Non-diabetes autoantibodies were detected in 20/44 (45%) 3-Screen positive patients who were positive for at least one thyroid autoantibody (TPO Ab and/or Tg Ab and/or TSHR Ab), while none were positive for the adrenal autoantibody 21-OHAb." (PMID 34533636, 2022).
atrophic thyroiditis (4 papers, 2013 to 2024). Atrophic thyroiditis is an organ-specific autoimmune disease characterized by thyroid autoantibodies, functional hypothyroidism, and absence of goiter. "Thyroid autoantibody levels differ between goitrous and atrophic thyroiditis in that inhibitory TSHR antibodies are higher in Ord’s thyroiditis." (PMID 28536577, 2017). "Anti-TSHR antibodies are found in 90% of GD patients, 0–20% HT, and 10–75% of atrophic thyroiditis patients." (PMID 28536577, 2017).
follicular adenomas (4 papers, 2007 to 2015). "Intriguingly, they also observed TSHr methylation in 20 % (2/10) of follicular adenomas." (PMID 26519197, 2015). "Interestingly, in benign cold follicular adenomas, a decrease of NIS mRNA levels was reported, whereas the expression of TG, TSHR and TPO was maintained." (PMID 22242190, 2012).
Hypercholesterolemia (4 papers, 2023 to 2025). An increased concentration of cholesterol in the blood. "In addition, higher TSH levels can induce steatosis via TSH receptor (TSHR) signaling, by also increasing hepatic gluconeogenesis, repressing hepatic bile acid synthesis, and causing hypercholesterolemia by decreasing 3-hydroxy- 3-methylglutaryl-CoA reductase phosphorylation." (PMID 37109577, 2023).
lung carcinoma (4 papers, 2011 to 2025). "Unexpectedly, two genes which are seldom reported to link to lung cancer risk, SBDS and TSHR, had the highest prevalence in our cohort." (PMID 37885353, 2024). "Case–control analysis showed SBDS c.184A>T(p.K62*), TSHR c.1574T>C(p.F525S), BRIP1 (BRCA1 interacting helicase 1) c.1018C>T(p.L340F), and MUTYH (mutY DNA glycosylase) c.55C>T(p.R19*) were significantly associated with increased lung cancer risk (q value < 0.05)." (PMID 37885353, 2024). "However, a role for TSHR in other cancers has not been elucidated, although infrequent mutations in lung cancer are recorded in COSMIC and TSHR has been shown to be lost at the DNA level, in some gastric cancers." (PMID 21781349, 2011).
metastatic disease (4 papers, 2015 to 2024). "Furthermore, the robust expression of the TSHR, being ubiquitous to the thyrocyte, still serves as an important and persistent regulator and physiological marker in primary and metastatic disease with the ability to target the BioNanofluid conjugates for a therapeutic potential." (PMID 26901566, 2016). "In addition, Zhou and colleagues demonstrated that PVT1 could be enriched by enhancer of zeste homolog 2 (EZH2), a marker of an advanced metastatic disease in numerous types of cancer including ATC, which may also contribute to the regulation of TSHR expression." (PMID 32760219, 2020).
multinodular goiter (4 papers, 2016 to 2024). Nodular goiter characterized by more than one discrete tissue mass. "In contrast, patient #230 with a multinodular goiter was identified with a previously known single-nucleotide mutation c.1801T>A in TSHR, which leads to a Tyr601Asn (p.Y601N) variant." (PMID 38194289, 2024).
thyroid dyshormonogenesis (4 papers, 2018 to 2024). "In conclusion, the percentage of patients with thyroid dyshormonogenesis and candidate variants in TSHR is 3.13%." (PMID 39337518, 2024). "Five patients with mild or severe thyroid dyshormonogenesis presented six TSHR variants, two unpublished." (PMID 39337518, 2024). "We aimed to genetically characterize patients with thyroid dyshormonogenesis with TSHR defects and to study in vitro the effect of the genetic variants to establish the genotype–phenotype relationship." (PMID 39337518, 2024). "Mutations in genes critical for TH biosynthesis, including sodium iodide symporter (NIS; SLC5A5), pendrin (PDS; SLC26A4), thyroglobulin (TG), thyroperoxidase (TPO), thyroid stimulating hormone receptor (TSHR), and dual oxidase 2 (DUOX2), have been causally linked to thyroid dyshormonogenesis." (PMID 38281222, 2024).
Anorexia (3 papers, 2019 to 2026). Lack of desire to eat (loss of appetite). "Together, our results may thus infer that down-regulation of CART and TSHR mRNA in the ARC could be a compensatory suppression rather than causal of anorexia in states of inflammation, perhaps to defend body weight in states of disease." (PMID 31829131, 2019).
COVID-19 (3 papers, 2021 to 2023). A disease caused by infection with severe acute respiratory syndrome coronavirus 2. "MPO and TSHR were overexpressed in both lung autopsies and whole blood tissue and were associated with more severe COVID-19." (PMID 34276672, 2021). "MPO and TSHR were the only two autoantigens overexpressed in lung autopsies and were shared between the lung and blood of severe COVID-19 patients." (PMID 34276672, 2021). "Interestingly, MPO and TSHR were increased in both lung autopsies and whole blood of severe COVID-19 patients." (PMID 34276672, 2021). "Endocrine-specific genes (e.g., HSD3B2, INS, IAPP, TSHR, FOXE1, LEP, and CRYGD) were deregulated in COVID-19 cases in an organ-specific manner." (PMID 37246981, 2023). "In whole blood study, seven autoantigens were upregulated in blood of severe COVID-19 patients (MPO, PRTN3, PADI4, IFIH1, TRIM21, PTPRN2, and TSHR), while four autoantigens (MPO, PRTN3, IFIH1, and PADI4) were increased in blood of mild patients." (PMID 34276672, 2021). "Comparison of COVID-19 blood transcriptomic with IAV and RSV revealed that MPO, PRTN3, and PADI4 were selectively upregulated in coronavirus infections, SARS-CoV-1 and SARS-CoV-2, while TSHR and PTPRN2 autoantigens were distinctive to SARS-CoV-2 infection." (PMID 34276672, 2021). "These two genes (TSHR and PTPRN2) did not increase in the mild COVID-19 and hence they were associated with more severe infection." (PMID 34276672, 2021).
glioma (3 papers, 2021 to 2025). A benign or malignant brain and spinal cord tumor that arises from glial cells (astrocytes, oligodendrocytes, ependymal cells). "TSH released by DCs promoted proliferation, especially in thyroid tumors and gliomas, which are tumors with high TSHR expression." (PMID 38275375, 2023). "TSH promotes the expression of the checkpoint protein PD-L1 and promotes proliferation and further tumor growth, which has been confirmed for several tumor types with high expression of the TSH receptors (TSHR), including gliomas." (PMID 38275375, 2023). "Therefore, the TSHR is also considered as a potential target for immunotherapeutic approaches for the treatment of gliomas." (PMID 38275375, 2023).
liver steatosis (3 papers, 2017 to 2025). "An interesting study demonstrated that liver steatosis and triglyceride content were significantly increased in TSHR+/+ HFD-fed mice compared to those in TSHR−/− mice, indicating an essential role for TSH in the pathogenesis of NAFLD." (PMID 36300106, 2022). "We observed that TSH could aggravate the triglyceride accumulation in hepatocytes induced by a high-fat diet in mice through the activation of sterol regulatory element binding protein 1c (SREBP-1c), and TSHR knockout mice (Tshr−/−) exhibited a relatively lower degree of liver steatosis." (PMID 28473851, 2017). "In rodents, TSHR was expressed in hepatocytes and was stimulated by TSH, which induced hepatic steatosis through SREBP1C." (PMID 41048433, 2025).
myositis (3 papers, 2022 to 2024). "CNVs on TSHR and FAN1 were significantly linked to myositis (p = 0.049 and p = 0.039)." (PMID 35053465, 2022). "Finally, CNVs on PRDM1 and CD274 were significantly linked to encephalitis, and CNVs on PRDM1, CD274, TSHR and FAN1 were significantly linked to myositis." (PMID 35053465, 2022). "Regarding CNVs, significant markers included PRDM1 deletions and IL1RN (IRAE), CD274 duplications and SLCO1B1 (hepatitis), PRDM1 and CD274 (encephalitis), and PRDM1, CD274, TSHR, and FAN1 (myositis)." (PMID 35053465, 2022). "Furthermore, the following genetic alterations were identified being associated with IRAE: SMAD3 (pancreatitis); CD274, SLCO1B1 (hepatitis); PRDM1, CD274 (encephalitis); PRDM1, CD274, TSHR, FAN1 (myositis)." (PMID 35053465, 2022).
nodular goiter (3 papers, 2016 to 2021). Goiter characterized by discrete tissue mass(es) that may or may not produce thyroid hormones. "TSHR expression in nodular goiter lesions may be associated with upregulated expression of transcription factors TTF-1 and PAX8." (PMID 27525008, 2016). "Results showed that, in addition to the increase in TSHR expression, nodular goiter lesions also expressed significantly more TTF-1 and PAX8 than normal thyroid tissues." (PMID 27525008, 2016). "Western blot analysis showed TSHR protein expression to be significantly greater in nodular goiter lesions than in the adjacent normal thyroid tissues." (PMID 27525008, 2016). "Upregulation of TSHR, TTF-1, and PAX8 is associated with low follicular lumen iodine content in nodular goiter." (PMID 27525008, 2016). "TSHR was localized in the basolateral membrane, and the immune reactivity of TSHR in nodular goiter was significantly higher than those in the control." (PMID 27525008, 2016). "In addition, the pathogenic TSHR Thr632Ile mutation was found in one sample of AUS cytology, and the final pathology indicated a nodular goiter with fibrosis and calcification." (PMID 34322384, 2021). "Likewise, immunohistochemical staining also showed there to be more TSHR staining was stronger in the basement membranes of cells in lesions than in normal tissues, indicating that TSHR is highly expressed in nodular goiter lesions." (PMID 27525008, 2016). "Immunohistochemistry was also performed to determine TSHR, TTF-1, and PAX8 expression in 30 nodular goiter and 30 control thyroid samples." (PMID 27525008, 2016). "Western blot was performed to determine the expression of TSHR, TTF-1, and PAX8 in 10 nodular goiter and 10 control thyroid samples." (PMID 27525008, 2016). "in addition to the increase in TSHR expression, the expressions of TTF-1 and PAX8 in nodular goiter lesions were also significantly higher than those in control tissues." (PMID 27525008, 2016). "The Spearman rank coefficient was performed to determine the correlation among the parameters of TSHR, TTF-1, PAX8, and iodine in 30 nodular goiter and control samples." (PMID 27525008, 2016). "Western blot immunohistochemistry was performed to assay TSHR, TTF-1, and PAX8 in thyrocytes of nodular goiter as well as in extranodular normal thyroid tissues." (PMID 27525008, 2016). "Epidemiological studies have suggested that iodine deficiency is the major risk factor of nodular goiter, which may be related to thyroid dysfunction caused by iodine deficiency and subsequent chronic thyroid stimulation caused by enhanced TSH level and its binding to TSHR." (PMID 27525008, 2016). "The TSHR, TTF-1, and PAX8 in nodular goiter were significantly higher than those in the controls." (PMID 27525008, 2016).
ovarian tumor (3 papers, 2016 to 2025). "By showing the promotion effect of thyrostimulin-TSHR signaling on EOC cell proliferation, to our knowledge this is the first report to demonstrate the direct involvement of TSHR signaling in certain aspect of ovarian tumor progression." (PMID 27273257, 2016). "In addition to EGFR, when we screened the RTKs commonly involved in ovarian tumor progression, we found that several RTKs with moderate expression levels can also be regulated by thyrostimulin-TSHR signaling in NIH:OVCAR 3 cells." (PMID 27273257, 2016). "For the remaining three regions, the 50 kb selected region on chromosome 5 includes two genes; the TSHR locus involved in metabolic regulation and reproduction process and GTF2A1, a candidate biomarker for detecting ovarian tumor." (PMID 30079080, 2018).
thyroid storm (3 papers, 2013 to 2025). "GD, also known as toxic diffuse goiter, is caused by autoantibodies that stimulate the thyroid-stimulating hormone receptor (TSHR), leading to symptoms such as thyroid enlargement, hypermetabolism, anxiety, irritability, and in severe cases, thyroid storm." (PMID 39456701, 2024).
Alzheimer disease (2 papers, 2022 to 2024). A progressive, neurodegenerative disease characterized by loss of function and death of nerve cells in several areas of the brain leading to loss of cognitive function such as memory and language. "Both LHR and TSHR have been implicated in controlling neuronal functions, with LHR signaling involved in learning and memory and changes in both LH and TSH/TSHR levels linked to ADHD and Alzheimer’s Disease." (PMID 39561202, 2024).
Anxiety (2 papers, 2022 to 2024). Intense feelings of nervousness, tension, or panic often arise in response to interpersonal stresses. "Finally, we found more recently that the modulation of TSHRs in the bed nucleus of the stria terminalis (BNST), which receives direct afferents from the MTu, influences anxiety responses, suggesting that TSHR signaling might, in fact, mediate psychosocial behaviors." (PMID 36052994, 2022).
arterial hypertension (2 papers, 2023 to 2024). "G-protein-coupled receptor kinases (GRKs) are implicated in the pathophysiology of arterial hypertension and thyrotropin receptor (TSHR)." (PMID 36874270, 2023).
Cognitive impairment (2 papers, 2021 to 2022). Abnormal cognition is characterized by deficits in thinking, reasoning, or remembering. "For instance, recent research showed that TSH receptor (TSHR) signaling deficiency-induced cognitive impairment indicated that TSH played a role in cognitive functions." (PMID 34887837, 2021).
colorectal cancer (2 papers, 2025). A primary or metastatic malignant neoplasm that affects the colon or rectum. "Next, CD8+ T cell exhaustion by cancer cell-released exosomes carrying thyroid-stimulating hormone receptor (TSHR) was reported in the case of colorectal cancer (CRC)." (PMID 41294803, 2025).
developmental delay (2 papers, 2015 to 2020). "Four genes (UCP2, UCP3, SCAPER, and TSHR) are related to the body weight (HP:0004324 and HP:0004323), and four genes (C2CD3, UCP2, ZMYND11, and TSHR) are involved in modulating the phenotype of globe developmental delay (HP:0001263)." (PMID 32973871, 2020).
diffuse sclerosis (2 papers, 2021 to 2023). "Expression of TSHR in classical subtype, microcarcinoma, follicular subtype, oncocytic subtype, insular subtype, diffuse sclerosis subtype and contiguous normal thyroid tissue." (PMID 36694763, 2023).
Hypokalemia (2 papers, 2014 to 2024). An abnormally decreased potassium concentration in the blood. "We found the G132R heterozygous mutation of thyroid stimulating hormone receptor (TSHR) gene in a patient with recurrent hypokalemia." (PMID 38241561, 2024).
Infertility (2 papers, 2018 to 2020). "In this rat model, TSHR is truncated at the second transmembrane domain, leading to CH phenotypes as what was observed in the patients, including dwarf, thyroid aplasia, infertility, TSH resistant as well as low serum thyroid hormone levels." (PMID 29507327, 2018). "Our structure-activity guided drug discovery, combined with preclinical monitoring of thyroid stimulating hormone receptor (TSHR) activity, allowed us to develop novel FSHR-AA suitable for use in future human infertility treatments." (PMID 33519465, 2020).
morbid obesity (2 papers, 2023). An excess of body weight, normally defined as an individual with a body mass index greater than 35 or a body weight greater than one hundred percent of ideal body weight. "In this regard, a prospective study that compared the expression of TSH receptor (TSHR) in SAT and VAT, by evaluating the extracted RNA before and after surgery, discovered decreased TSH and TRalpha1 receptor expression in the adipose tissue of patients with morbid obesity." (PMID 38201918, 2023).
myocarditis (2 papers, 2021 to 2024). Myocarditis is a condition that is characterized by inflammation of the heart muscle (myocardium). "A mouse model for GD was successfully established by three immunizations with recombinant adenovirus expressing the human TSHR, giving us hope to study the development of this myocarditis." (PMID 34307494, 2021).
nonautoimmune congenital hyperthyroidism (2 papers, 2023 to 2025). "Nonautoimmune hyperthyroidism (NAH), caused by constitutively active mutants of the thyrotropin receptor (TSHR) gene, is recommended to be treated with total thyroidectomy followed by radioiodine administration." (PMID 37908476, 2023).